C9orf85 (chromosome 9 open reading frame 85)
Synonyms: MGC61599
Tractability: No criterion of Open Targets' tractability assessment is met for any kind of drug.
Gene: Protein-coding gene on chromosome 9 (71,911,457 to 71,986,054, forward strand). Ensembl gene ENSG00000155621.
Subcellular location (Human Protein Atlas): Golgi apparatus; Nucleoli; Nucleoplasm
Genetic constraint (gnomAD): Loss-of-function variants: 7 observed, 8.58 expected, observed/expected ratio (o/e) 0.82, 90% interval 0.46 to 1.51. That is too few expected variants to judge how well the gene tolerates losing a copy. Missense variants: 93 observed, 102.23 expected, observed/expected ratio (o/e) 0.91, 90% interval 0.77 to 1.08. Synonymous variants: 20 observed, 34.21 expected, observed/expected ratio (o/e) 0.58, 90% interval 0.41 to 0.85.
Homologues: Orthologues: macaque C15H9orf85 (99% identical), guinea pig C9orf85 (89% identical), dog C9orf85 (87% identical), pig C9orf85 (87% identical), rabbit C9orf85 (82% identical), mouse 1110059E24Rik (82% identical), rat C1h9orf85 (82% identical), chimpanzee C9H9orf85 (71% identical), tropical clawed frog c1h9orf85 (64% identical), zebrafish C5H9orf85 (55% identical), Drosophila melanogaster CG8675 (44% identical).
Diseases named in the same sentence as C9orf85 in open-access papers:
C9orf85 is named in the same sentence as 4 diseases in open-access papers, as found by Europe PMC text mining. Sharing a sentence is not in itself a finding about the gene and the disease. The quoted sentences say what the papers report.
malnutrition (1 paper, 2022). Inadequate nutrition resulting from poor diet, malabsorption, or abnormal nutrient distribution. "In particular, the differentially expressed proteins (e.g., C9orf85 and CXorf38) identified in the ZIP8-KO cells could be potential targets for diagnosing and/or treating a wide range of human ZIP8-associated diseases, including but not limited to malnutrition, viral infection, and cancers." (PMID 36330220, 2022).
cancer (1 paper, 2022). A tumor composed of atypical neoplastic, often pleomorphic cells that invade other tissues. "Specifically, CXorf38 was significantly co-expressed with ZIP8 in 18 out of 40 cancer types, whereas C9orf85 was only in nine out of 40 cancer types." (PMID 36330220, 2022). "Furthermore, clinical-based bioinformatic analysis indicated that positive correlations between the gene expressions of ZIP8 and C9orf85 or CXorf38 were observed in multiple cancer types." (PMID 36330220, 2022). "In addition, we performed clinical-based bioinformatic analysis to evaluate the potential connections between the gene expressions of ZIP8 and C9orf85 or CXorf38 in multiple cancer types." (PMID 36330220, 2022).
tumor (1 paper, 2023). "This analysis revealed a significant enrichment in the YC:YR ratio in the responsive tumor samples over the non-responsive samples for each gene, but particularly for C9orf85 and PRORP." (PMID 37996663, 2023).
C9orf85 also shares sentences with these, for which no sentence is quoted: viral infection (1 paper).